HIF1A (hypoxia inducible factor 1 subunit alpha)
Diseases named in the same sentence as HIF1A in open-access papers (continued):
Sharing a sentence is not in itself a finding about the gene and the disease.
pancreatic cancer (continued). "Additionally, we examined HIF1α expression in mouse specimens and found that the proportions and staining signals for HIF1α were substantially lower than those in control tumors, suggesting that the increased HIF1α expression might result from Pfn1 downregulation in pancreatic cancer." (PMID 25103363, 2014). "Taken together, our study demonstrates for the first time that MUC17 expression is enhanced by the HIF1α-mediated hypoxic response and that DNA methylation of HRE is a key determinant of the hypoxic inducibility of MUC17 in pancreatic cancer." (PMID 22970168, 2012). "Hypoxia is a characteristic feature in pancreatic cancer tissue, and besides the VEGF production, hypoxia alters intracellular signals by up-regulating HIF1α." (PMID 22934011, 2012). "To identify the function of HIF-1α and HIF-2α in hypoxia-induced expression of CX3CR1 in pancreatic cancer, we used three specific siRNAs targeting HIF-1α or HIF-2α and all of them effectively reduced HIF-1α or HIF-2α expression." (PMID 22952674, 2012). "Our results show that MUC17 is induced by HIF1α mediating hypoxic response, and the specific DNA methylation determines the hypoxic inducibility of MUC17 in pancreatic cancer cells." (PMID 22970168, 2012). "We have used the tumor tissues from control and CDF-treated animals and here we show that CDF treatment led to decreased expression of Ki-67, EZH2, HIF-1α, VEGF, and EpCAM in pancreatic tumor remnants as assessed by immunohistochemistry." (PMID 23272057, 2012). "Taken together, our data provides convincing evidence that BITC inhibits pancreatic tumor angiogenesis by targeting STAT-3 and inhibiting HIF-1α/VEGF/MMP-2/Rho-GTPases." (PMID 22016776, 2011). "Herein, we demonstrated that hypoxia or overexpression of HIF-1α activated NF-κB and promoted EMT in pancreatic cancer cells." (PMID 21887310, 2011). "Studies demonstrate that radiation enhances glycolysis in pancreatic cancer cells, raising lactate levels and promoting MDSC activity via the GPR81/mTOR/HIF-1A/STAT3 pathways, thus contributing to an immunosuppressive microenvironment and tumor progression, recurrence, and radioresistance." (PMID 41424847, 2026). "HIF-1α -Snail signaling pathway and FOXM1 are reported to induce epithelial-mesenchymal transition (EMT), which is involved in the metastasis and infiltration of pancreatic cancer." (PMID 40063301, 2025). "Indeed, the HIF‐1α‐induced activation of LDHA and its facilitation of lactate production have been reported in various diseases, such as pancreatic cancer, supporting the findings of our study." (PMID 40176272, 2025). "Consequently, upregulated SIRT1 enhances HIF-1α stability through deacetylation, resulting in glycolysis and GEM resistance in recipient pancreatic cancer cells." (PMID 40004471, 2025). "The hypoxic tumor microenvironment in pancreatic cancer stabilizes HIF-1α to drive pro-survival gene expression; however, whether HIF-1α directly regulates ECM components, such as collagens, remains controversial." (PMID 40406267, 2025). "Thus, HIF-1α-induced BX111 promotes the proliferation and invasion of pancreatic cancer cells via the activation of ZEB1 transcription." (PMID 40861273, 2025). "Beyond this general metabolic alteration, MTAP deficiency leads to enhanced expression of hypoxia-inducible factor 1α (HIF1-α) and activation of RIO kinase 1 (RIOK1) in pancreatic cancers, prompting metabolic adaptation towards a glycolytic phenotype and de novo purine synthesis." (PMID 41439984, 2025). "Expression of HIF-1α and TGF-β1 in pancreatic cancer tissues and normal tissues." (PMID 40406267, 2025). "These opposite expressional changes between MiaPaCa-2and Panc-1 cells under miR-210 KO and hypoxic conditions suggestedthat miR-210 was correlated with HIF1-α, EMT, and CSC-relatedmiRs and pathways, while the downstream effects were various amongdifferent pancreatic cancer cell lines." (PMID 39651070, 2024).
pancreatic cancer (continued). "To identify whether HIF-1α mediates the regulatory mechanism governing MUC1-mediated regulation of SAT1, we assessed the expression of HIF-1α in MUC1-depleted pancreatic cancer cell lines." (PMID 38547055, 2024). "Interestingly, our results showed HIF1α and GLI-1 expressions were also regulated by EZH2, which is consistent to the previous reports that the similar regulatory role of EZH2 in HIF1α and GLI-1 expressions has been shown in lung and pancreatic cancer cells." (PMID 38664825, 2024). "Furthermore, by creating a positive feedback loop involving AKT/HIF-1α signaling, the overexpression of lncRNA CASC9 under hypoxic settings enhances glycolysis and the epithelial-mesenchymal transition in pancreatic cancer." (PMID 39346921, 2024). "Additionally, miR-421 directly represses SIRT3, leading to altered HIF-1α expression through the modulation of histone acetylation at H3K9, in pancreatic cancer." (PMID 39682281, 2024). "Notably, in pancreatic cancer, decreased expression of EGLN2 and EGLN3 resulted in the induction of angiogenic factors by HIF1A and TGF-β1 pathway and poor patient OS." (PMID 38928200, 2024). "In our previous research, we found that 8a inhibited the growth of pancreatic tumors in the pancreatic cancer xenograft model and, on this basis, we evaluated the angiogenesis of pancreatic cancer by detecting the expression level of CD31 and HIF-1α using immunohistochemical staining." (PMID 37888452, 2023). "HIF-1α plays a vital role as a transcriptional regulator of hypoxia-induced EMT, and a significant correlation exists between HIF-1α and HDAC1 expression in pancreatic cancer." (PMID 36902253, 2023). "In addition, in pancreatic cancer (PCA), HIF-1α could bind to the region at upstream of circZNF91 transcription start sites and promoted endogenous transcription of circZNF91, thus regulating HIF-1α-associated glycolysis and increased GEM resistance in normoxic PCA cells." (PMID 37213665, 2023). "The p65 subunit of NF-κB or HIF-1α is downregulated by siRNA to reverse the EMT phenotype under hypoxic conditions in vitro, inhibits the proliferation of pancreatic cancer cell lines (PANC-1, BxPC3), induces apoptosis, and enhances the efficacy of gemcitabine in treating pancreatic cancer." (PMID 37046617, 2023). "Notably, neutrophils in the pancreatic tumor of OT mice co-expressed high levels of GLUT1 and HIF-1α." (PMID 36614196, 2023). "The inhibitory effect of HIF-1α has been shown in human pancreatic cancer cells S2-013 and CD18, but not in HCC cells yet." (PMID 35283421, 2022). "LncRNA ENST00000480739 may suppress pancreatic cancer invasion, metastasis and EMT by indirectly inhibiting HIF-1α expression." (PMID 35819532, 2022). "Besides, HDACI can inhibit tumor angiogenesis by regulation of hypoxia-inducible factor-1 alpha (HIF-1a) and vascular endothelial growth factor (VEGF), and inhibit pancreatic cancer metastasis by reverse of epithelial to mesenchymal transition (EMT)." (PMID 35062876, 2022). "HIF1A enhances EMT and migration in pancreatic cancer stem cells." (PMID 36139919, 2022). "Thus, BITC is a strong anti-cancer agent effective against pancreatic cancer acting via inhibition of PI3K/AKT/FOXO-, STAT-3-, and STAT-3-mediated HIF-1α/VEGF/Rho-GTPases signaling axes." (PMID 36428575, 2022). "Migration and Invasion Inhibitory Protein (MIIP) has recently been identified as an inhibitor of tumor development and constitutes a negative feedback loop with HIF1α in pancreatic cancer." (PMID 35651786, 2022). "In addition, the interaction between lncRNAs and HIF-1α and m6A RNA methylation also have an impact on tumor metastasis and EMT in pancreatic cancer." (PMID 35819532, 2022). "Our previous study also demonstrated miR-548an could be transcriptionally downregulated by HIF1α/HDAC1, further suppressing tumorigenesis of pancreatic cancer." (PMID 34930270, 2021). "In pancreatic cancer, lncRNA-BX111887 was reported to be induced by HIF-1α in response to hypoxia." (PMID 33407675, 2021).
pancreatic cancer (continued). "Furthermore, cell colony formation assays showed that both anti-HIF-1α VHH212 and digoxin combination with gemcitabine dramatically inhibited cell proliferation in pancreatic cancer cell lines." (PMID 33830713, 2021). "Moreover, results in this experiment show remarkable synergistic effects observed in pancreatic cancer cells treated with selective STAT3 inhibitors, an EGFR/ErbB2 inhibitor, and a HIF-1α inhibitor." (PMID 33544704, 2021). "Our mechanism derived biomarkers (HIF-1α and galectin-3) suggest the evaluation of Hsp90 inhibitors in pancreatic cancer, and not just in kinase-addicted cancers." (PMID 33672199, 2021). "The phosphorylated Erk could increase the transcriptional activation function of HIF-1α, and thus stimulates the biological function of VEGF, for instance, survival and metastasis of pancreatic cancer." (PMID 34336654, 2021). "Chronic stress induces pancreatic tumor growth and angiogenesis by upregulated expression of matrix metallopeptidase-2 (MMP-2), MMP-9, and vascular endothelial growth factor (VEGF), mediated by a HIF-1α-dependent β-AR signaling pathway." (PMID 33419318, 2020). "Furthermore, HIF-1α was found to mediate hedgehog signaling for EMT and invasion in pancreatic cancer cells and the silencing of HIF-1α would reverse hypoxia-induced hedgehog signaling activation." (PMID 32322559, 2020). "In pancreatic cancer, hypoxia-induced phosphorylation of ERK1/2 activated HIF-1α, increasing the accumulation of HIF-1α in the cytoplasm and translocating to the nucleus, and then bound to the HRE of ABCG2 and promoted its transcription, thereby enhancing the drug resistance." (PMID 32587480, 2020). "The study showed xylene derivative TEL03 could bind to HIF-1α to block the combination of HIF-1α and p300, and induce the degradation of HIF-1α by proteasome pathway in pancreatic cancer." (PMID 32587480, 2020). "Conversely, TLR3 was shown to induce the Warburg effect and aid tumor cells in adapting to the hypoxic milieu, whereas HIF-1α and TLR4 may synergistically promote development of pancreatic cancer." (PMID 32707920, 2020). "In pancreatic cancer cells, Mint3 depletion did not affect HIF-1α protein levels, and HIF-1α depletion also did not affect Mint3 expression." (PMID 32826949, 2020). "In addition, research showed HIF-1α bound directly to the HRE of cyclophilin A (CypA) and upregulated its expression, which inhibited pancreatic cancer cells apoptosis." (PMID 32587480, 2020). "Moreover, HIF-1α increased Snail transcription through binding to its HRE, contributing to EMT in pancreatic cancer." (PMID 32587480, 2020). "Thus, the Mint3/FIH-1/HIF-1α axis increases SKP2 mRNA levels, at least in part, by enhancing the promoter activity of SKP2 in pancreatic cancer cells." (PMID 32826949, 2020). "In addition to the acceleration of HIF-1α degradation, targeting the HIF-1α signaling pathway is also a momentous avenue to impede the progression of pancreatic cancer." (PMID 32587480, 2020). "Analogously, pharmacologic ascorbate (P-AscH) rapidly degrades HIF-1α in a proteasome-dependent pathway in pancreatic cancer cells which is independent of 2-oxoglutarate-dependent prolyl hydroxylase (PHD-2)." (PMID 32587480, 2020). "We therefore reasoned that elevated HIF1α in pancreatic tumor tissues could lead to upregulated AGR2 expression as well, which was indeed confirmed by higher AGR2 mRNA levels in pancreatic tumor tissues than adjacent normal tissues." (PMID 32322663, 2020). "Besides, curcumin, a natural polyphenol present in turmeric, and its analogues suppress the expression of HIF-1α by inhibiting its interaction with HSP90 and NF-κB signaling pathway in pancreatic cancer." (PMID 32587480, 2020). "Notably, TX-2098, a hypoxia cytotoxin, directly down-regulated the protein level of HIF-1α and its downstream targets such as VEGF, glucose transporter type 1 and aldolase A in pancreatic cancer, inhibiting its progression." (PMID 32587480, 2020).
pancreatic cancer (continued). "Therefore, the present study demonstrates a lncRNA-interacted feedback of HIF-1α and FOXC2 which is involved in pancreatic cancer progression during hypoxia microenvironment." (PMID 31367258, 2019). "Furthermore, dying cell derived HMGB1 activates TLR2/YAP/HIF-1α pathways and induces neighboring CD133− pancreatic cancer cells dedifferentiation, which is an important signaling event underlying tumor relapse following radiotherapy." (PMID 31558702, 2019). "HIF-1α expression was evaluated by immunohistochemistry in clinical pancreatic cancer tissues with or without diabetes mellitus." (PMID 30455857, 2018). "Immunohistochemical staining was used to detect the expression of HIF-1α in normal pancreas specimens and in pancreatic cancer specimens from patients with or without diabetes." (PMID 30455857, 2018). "The detection of hif-1α/β-catenin/hif-2α complex in pancreatic cancer (data not shown) also suggested a noncompetitive interaction between hif-1α and hif-2α for β-catenin binding." (PMID 28705232, 2017). "HIF-1α stimulates SHH expression in fibroblasts and cardiomyoblasts and SMO in pancreatic cancer, which suggests that, in situ, hypoxia could also induce SHH signaling in WJ-MSC." (PMID 28962669, 2017). "Moreover, STAT3 activation induced by Pim-3 increases the transcription of Hif-1α, thereby up-regulating the expression of MDR1 (P-glycoprotein) gene, resulting in reduced chemosensitivity in human pancreatic cancer cells." (PMID 29069816, 2017). "Our results showed that proteasomal activity following triptolide treatment was marginally decreased, indicating that this did not contribute significantly to stabilization of HIF-1α in the pancreatic cancer cells." (PMID 28801636, 2017). "We next studied whether HIF-1α, a transcriptional regulator of VEGF-A, is also up-regulated in cytokine-stimulated pancreatic cancer cell lines." (PMID 27637085, 2016). "Furthermore, knockdown of HIF-1α and ICI118, 551 (a β2-AR selective antagonist) abrogates NNK-induced pancreatic cancer proliferation and invasion in vitro and inhibits NNK-induced pancreatic cancer growth in vivo." (PMID 26497365, 2016). "In addition, miR-145 over-expression markedly suppressed protein expression levels of p70S6K1, p-S6, HIF-1α and VEGF in pancreatic cancer cells, confirming that miR-145 targets p70S6K1 and inhibits relative signaling molecules in these cells." (PMID 27765914, 2016). "Hypoxia-inducible factor-1α (HIF-1α), one of the key players of cell survival response to hypoxia, was shown to convert non-stem pancreatic cancer cells into pancreatic cancer stem-like cells through autophagic mechanisms." (PMID 26697128, 2016). "Further, treatment of the MiaPaca2 pancreatic cancer cell line with the p38 inhibitor SB203580 caused an increase in VHL-HIF-1α binding suggesting that p38 contributes to HIF-1α stabilization, though no half-life measurements were performed." (PMID 26942179, 2016). "Since upregulation of VEGF-A, an essential driver of blood vessel formation, occurs mainly via stabilization of HIF-1α, we sought to investigate whether PKM2 contributes to VEGF secretion in hypoxic pancreatic cancer cells." (PMID 26739387, 2016). "The levels of HIF-1α were correlated with phosphoinositide-dependent kinase-1, lactate dehydrogenase A and pyruvate kinase, muscle 2 expression and inhibition of HIF-1α repressed pancreatic cancer cell growth." (PMID 26018028, 2015).
pancreatic cancer (continued). "In conclusion, we described a novel regulatory mechanism whereby pancreatic cancer proliferation is inhibited by the interaction of Pfn1 and SIRT3 to destabilize HIF1α, which results in reduced expression of HIF1α target genes that coordinate aerobic glucose consumption." (PMID 25103363, 2014). "Our data showed that conversation of non-stem pancreatic cancer cells into pancreatic CSCs resulted from the elevated HIF-1α and activated autophagy." (PMID 24305593, 2013). "Intermittent hypoxia enhanced stem-like properties of non-stem pancreatic cancer cells and stimulated the levels of HIF-1α, LC3-II and Beclin." (PMID 24305593, 2013). "The conversation of non-stem pancreatic cancer cells into pancreatic cancer stem-like cells was induced by HIF-1α and autophagy." (PMID 24305593, 2013). "Also, Wei and colleagues reported that STAT3 activation regulates the expression of VEGF and human pancreatic cancer angiogenesis Furthermore, several papers described the role of STAT3 as a potential modulator of HIF-1α-induced VEGF signaling in cancer cells." (PMID 21731766, 2011). "Of note, in vitro and in vivo studies have also shown that use of a novel selective HIF-1α inhibitor potentiates fractionated radiation-induced pancreatic cancer cell death, with or without combined treatment with 5-fluorouracil or gemcitabine." (PMID 24281221, 2010). "In human pancreatic cancers, 56% of pancreatic cancers show positive immunehistochemical staining for HDAC1, and the co-expression of HDAC1 and hypoxia-inducible factor-1α (HIF-1α) markedly correlates with poor prognosis." (PMID 24281216, 2010). "As pancreatic cancer grows under hypoxic conditions, it was tested whether PHD3 overexpression influences HIF-1α stabilisation and VEGF secretion." (PMID 20978507, 2010). "Of note, free CHC+US treatment showed little impact on tumor growth inhibition, cell damage induction, and HIF‐1α down‐expression, which meant that CHC enabled SDT responses only when delivered by our nanoplatform, as free administration of CHC had limited access to the pancreatic tumor site." (PMID 38308196, 2024). "Apigenin could effectively downregulate HIF-1α and GLUT-1 mRNA and protein expression in human pancreatic cancer S2-013 and CD18 cells, and overcome any hypoxia-mediated elevation of GLUT-1 gene expression, thereby suppressing aerobic glycolysis and promoting tumor cell apoptosis." (PMID 36339566, 2022). "Emodin and rhein are anthraquinone components derived from Rheum palmatum that can inhibit HIF-1α and diminish the downstream glucose regulating molecules, GLUT1, as well as reduce the expression of HK2 and PFK1 and prevent the Warburg Effect of human pancreatic cancer cells." (PMID 36339566, 2022). "We found that after the treatment of pancreatic cancer BxPC-3 cells with 2-DG in different concentrations, with the concentration increasing, the protein level of P-STAT3 decreased significantly, and qPCR showed that STAT3 and its downstream target genes, VEGF and HIF1A were also decreased." (PMID 33607990, 2021). "In pancreatic cancer, LB-1 decreased the activity of HIF-1α via inhibiting its upstream pathway PI3K/Akt/mTOR, moreover, LB-1 could inhibit the connection between HIF-1α, p-STAT3 and p300, repressing VEGF expression, in addition, LB-1 accelerated HIF-1α degradation by ubiquitin–proteasome pathway." (PMID 32587480, 2020). "HIF-1α could recruit HDAC1 to the promoter of pri-miR-548an to transcriptionally suppress miR-548an expression, resulting in the upregulation of the EMT marker vimentin, which facilitates the proliferation and invasion of pancreatic cancer cells." (PMID 32014012, 2020). "Additionally, the study elucidated that HIF-1α-induced autophagy mediated the conversion of non-stem pancreatic cancer cells to pancreatic cancer stem cells in hypoxia, enhancing the malignancy of pancreatic cancer." (PMID 32587480, 2020). "Similarly, in hypoxic pancreatic cancer cells, ERK1/2 activates HIF-1α and up-regulates BCRP." (PMID 31117237, 2019).